GSK3B (glycogen synthase kinase 3 beta)
Diseases named in the same sentence as GSK3B in open-access papers (continued):
Sharing a sentence is not in itself a finding about the gene and the disease.
breast cancer (continued). "In support of this, complete inhibition of GSK3β with MeBIO caused a significant increase in GLI1 expression, whereas the introduction of constitutively active GSK3β by the transfection of breast cancer cells enhanced drug retention ability that is abrogated by OPN treatment." (PMID 34638233, 2021). "In addition, relationships between KRT19, FKBP10 and GSK3B expression and clinicopathological features from TCGA breast cancer cohort (n = 1083) were also explored." (PMID 35096583, 2021). "GSK-3β could interact with PD-L1 and play an important role in antitumor T-cell immunity of breast cancer." (PMID 35095838, 2021). "Moreover, PARPi administration to breast cancer cell lines further enhance PD-L1 by inactivating GSK3β, thus explaining the benefit obtained by the combination of PARPi and anti-PD-L1 therapy." (PMID 34220848, 2021). "The results suggest that the AKT/GSK3β signaling pathway may indicate a viable clinical treatment target in breast cancer." (PMID 34904014, 2021). "Furthermore, several natural products including resveratrol, berberine, and curcumin have been known to modulate GSK-3β activity and have varying effects on in vitro models of colon cancer, melanoma, and breast cancer." (PMID 34356465, 2021). "Moreover, GSK3β inhibition resulted in a significant increase in the nuclear expression of Cyclin D1 in SHP2 knockout breast cancer cells." (PMID 32944401, 2020). "GSK3β’s phosphorylation in breast cancer was reported to be reduced by lncRNA NLIPMT." (PMID 32795333, 2020). "The inhibitory phosphorylation of GSK3β might enhance cell proliferation and migration via β-catenin/cyclin D1 signaling pathway in breast cancer." (PMID 32466334, 2020). "In addition, estrogen E2 enhances the expression of NRF2-dependent antioxidant genes in normal, malignant BRCA1-deficient cells as well as MCF-7 breast cancer cells, via the PI3K/ glycogen synthase kinase 3 beta (GSK3β) pathway." (PMID 32354000, 2020). "Moreover, overexpression of either GSK-3α or GSK-3β activates mTORC1 and suppresses autophagy in breast cancer cells." (PMID 31882719, 2019). "Finally, GSK3β expression is increased in breast cancer correlating with a worse prognosis for TNBC patients." (PMID 30845991, 2019). "In addition, we further explored the mechanism of IQUB in promoting breast cancer by activating the Akt/GSK3β/β‐catenin signaling pathway, which would provide a new idea for better comprehension of breast cancer pathogenesis and breast cancer targeted therapy." (PMID 29968965, 2018). "Thus, in the present study, the antitumor mechanism of Moracin D was elucidated in breast cancer cells in association with FOXM1 and β-Catenin/GSK3β signaling with the possibility of a potent pharmaceutical for future agricultural commercialization." (PMID 30201862, 2018). "Furthermore, IQUB overexpression or knockdown combined with treatment of Licl or MG‐132 showed that IQUB activated Akt to promote GSK3β phosphorylation, which in turn activated Wnt/β‐catenin signaling pathway in breast cancer cells." (PMID 29968965, 2018). "IQUB could activate Akt/GSK3β/β‐catenin signaling pathway, promoting proliferation and migration of breast cancer cells." (PMID 29968965, 2018). "MCP-1 was shown to activate GSK3β signaling in human breast carcinoma cells." (PMID 29976212, 2018). "Interestingly, trichostatin A, a histone deacetylase inhibitor (HDACI), induces apoptosis through GSK-3β in MCF-7 breast cancer cells, and a specific GSK-3 inhibitor (SB-415286) induces apoptosis in different leukemia cell lines." (PMID 29379583, 2017). "In the present study, we examined whether ID extract inhibits Akt and Gsk-3β phosphorylation on breast cancer cells." (PMID 28134814, 2017). "However, in additional to mediating EGFR glycosylation, RPN2 can physically interact with both Y216-phosphorylated and unphosphorylated GSK3β to regulate the malignancy of breast cancer." (PMID 29069815, 2017).
breast cancer (continued). "Furthermore, overexpression of DACT2 in MB231 breast cancer cell lines resulted in a profound reduction of both total and phosphorylated forms of Akt and GSK-3β." (PMID 27708215, 2016). "Thus, we finally selected GSK-3β for further functional studies to assess the effect of miR-3646 on Doc resistance of breast cancer cells." (PMID 27045586, 2016). "Taken together, our results suggest that miR-3646-mediated Doc resistance of breast cancer cells maybe, at least in part, through suppressing expression of GSK-3β and resultantly activating GSK-3β/β-catenin signaling pathway." (PMID 27045586, 2016). "Kinase-inactive GSK3β in murine mammary glands can promote breast cancer development." (PMID 26910843, 2016). "To determine whether in vivo exposure to radiation could induce Thr390 phosphorylation of GSK3β in humans, we performed a pilot study with breast cancer patients undergoing local radiotherapy as the first regimen of therapy." (PMID 26822034, 2016). "Publically available algorithms (miRanda, TargetScan) were used to explore the precise mechanism by which miR-1229 activates the Wnt/β-catenin pathway in breast cancer, and showed that GSK-3β, APC, and ICAT might be potential targets of miR-1229." (PMID 26992223, 2016). "The present identify miR-3646, is obviously up-regulated and consequently leads to suppression of GSK-3β in breast cancer cells, suggesting that miR-3646 may modulate the drug resistance by targeting GSK-3β." (PMID 27045586, 2016). "Our finding that HNK modulates Akt, GSK3β, and β-catenin, key components of leptin-signaling network in breast cancer cells, prompted us to further explore whether HNK treatment can also inhibit MTA1, Wnt1, β-catenin and cyclin D1 in the presence of leptin." (PMID 26036628, 2015). "For example, the experiment by Sokolosky GSK-3β activity could result in the altered chemosensitivity of MCF-7 breast cancer cells to ADR through regulation of the PI3K/Akt/mTORC1 pathway by phosphorylating signaling molecules such as PTEN and TSC2." (PMID 26066793, 2015). "Sokolosky’s experiment showed that inhibition of GSK-3β activity could result in altered chemosensitivity of MCF-7 breast cancer cells to ADR through regulation of PI3K/Akt/mTORC1 pathway activity by phosphorylating signal molecules such as PTEN and TSC2." (PMID 26066793, 2015). "Thus, our results strongly suggest that APP-mediated regulation of AKT/FOXO and AKT/GSK3β pathways are playing a significant role for breast cancer development." (PMID 25491510, 2014). "The increased nuclear localization of GSK-3β in breast cancer tissues has also been reported." (PMID 24765134, 2014). "Therefore, the role of AGK-modulation of GSK-3β activity in breast cancer cells is currently under investigation by our group." (PMID 24886245, 2014). "Consistent with our previous reports that Bmi-1 could regulate Akt activity in breast cancer cells and the Akt/GSK-3β/Snail pathway in NPC cells, the overexpression of Bmi-1 facilitated the expression of phosphorylated Akt." (PMID 21276221, 2011). "Previous studies demonstrated Akt could regulate the activation of GSK-3β, p70S6K1 and mTOR, and all of them were able to activate Rac1, suggesting that hypoxia stimulates Rac1 activation in breast cancer cells by activating PI3K/Akt signaling." (PMID 21980400, 2011). "In contrast, GSK-3β activation decreased cell proliferation of breast cancer cells, prostate cancer cells, and colon cancer cells as well as survival of prostate cancer cells, breast cancer cells, and colorectal cells." (PMID 20704706, 2010). "In addition, CCL18 can bind with PITPNM3, inducing EMT, migration, and invasion of non-small cell lung cancer and breast cancer via PI3K/Akt/GSK3β/Snail signaling pathway and engulfment and cell motility 1/dedicator of cytokinesis protein 4 CRK binding protein signaling pathway, respectively." (PMID 35609322, 2022).
breast cancer (continued). "E3 ubiquitin ligase A20 monoubiquitinates Snail at threelysine residues, which reduces the affinity of Snail for GSK-3β andmaintains its nuclear localization, facilitating breast cancer (BC) cell EMTinduced by transforming growth factor β (TGF-β1)." (PMID 33959388, 2021). "Moreover, elimination of natural killer cell cytotoxicity via promoted expression of natural killer (NK) cell ligands is done by pSer535-eIF2B following the expression of pSer9-GSK-3β (inactive GSK3β) and generation of ROS, which promotes breast cancer growth and metastasis." (PMID 34249670, 2021). "However, it was also reported that GSK3β inhibition could decrease proliferation of rapamycin-insensitive breast cancer cells, suggesting that GSK3β can modulate cell proliferation by both S6K1-dependent and -independent mechanisms." (PMID 33081032, 2020). "Therefore, we speculated that GSK3B has a similar function as β-catenin in breast cancer, but further verification is still needed." (PMID 30181805, 2018). "Similarly, GSK3B is also highly expressed in breast cancer patients." (PMID 30181805, 2018). "However, to formally exclude this mechanism in colorectal cancer cells we determined whether SFN treatment reduces the inhibiting phosphorylation of GSK3β at serine 9, as described for breast cancer cells." (PMID 30338040, 2018). "Given that previous studies have shown that GSK-3β is a promising target for cancer treatment, further research on the mechanism of PSAT1 and GSK-3β in ER-negative breast cancer may provide more valuable insight into optimal treatments for this type of breast cancer." (PMID 29216929, 2017). "Therefore, we hypothesized miR-30c/CTHRC1 axis might also exert its role by targeting GSK-3β/β-catenin signaling in breast cancer." (PMID 28697793, 2017). "Our data demonstrated that CTHRC1, negatively regulated by miR-30c, promoted cell proliferation, invasion and migration and suppressed cell apoptosis in breast cancer, which might be by activating GSK-3β/β-catenin signaling and inhibiting Bax/Caspase-9/Caspase-3 signaling respectively." (PMID 28697793, 2017). "Moreover, Western blot analysis of the proteins participating in the Wnt/β-catenin pathway showed that the levels of NRIP1, β-catenin and GSK-3β phosphorylation were elevated by NOP14-overexpressing in three breast cancer cell lines (MDA-MB-231: ER-negative; MCF7 and BT474: ER-positive)." (PMID 26213846, 2015). "Thus, the phosphorylation of CRMP2 in the nuclei of breast epithelium by Cdk5 and GSK-3β may contribute to breast cancer progression." (PMID 24765134, 2014). "Thus it prompted us to speculate whether GSK3β inactivation was required for Aur-A to activate mTOR signaling in breast cancer." (PMID 25115395, 2014). "For instance, in breast cancer, SNHG5 regulates proliferation through the SNHG5–miR-154-5p–PCNA axis; in HCC, it sponges miR-26a-5p to relieve repression of GSK3β, leading to Wnt/β-catenin pathway activation and EMT induction." (PMID 41550840, 2026). "Similar ceRNA networks involving SNHG5 have been reported in other malignancies, including the SNHG5–miR-154-5p–PCNA axis in breast cancer and the SNHG5–miR-26a-5p–GSK3β axis in HCC." (PMID 41550840, 2026). "In PIK3CA-mutant ER + breast cancer, PI3Kα enhances Wnt activation via INPP4B-mediated GSK3β degradation." (PMID 40804731, 2025). "Among these pathways, the p-ERK and p-AKT signaling in breast cancer, the LRP6/GSK3β/β-catenin axis in NPC, and the cytosolic fatty-acid-binding protein 7 (FABP7)/PPARγ axis in malignant gliomas have been reported." (PMID 40001923, 2025). "In breast cancer, KRT19 is found to mediate cell cycle arrest, a typical characteristic of senescence by physically interacting with GSK3β and thus restrain GSK3β-dependent degradation of cyclin D3." (PMID 41345704, 2025). "The AKT/GSK3β/FYN axis is well-studied for regulating NRF2 nuclear export in non-cancerous, but is poorly understood in cancer, particularly breast cancer." (PMID 39984471, 2025).
breast cancer (continued). "Knockdown of Aurora B can suppress AKT/GSK3β/Snail1 signaling, reverse EMT, and reduce the metastatic capability of breast cancer cells in vitro and in vivo." (PMID 39892781, 2025). "In breast cancer, SIRT2 inhibits the acetylation of GSK3β in CD8(+) effector memory T cells, leading to an increase in the number of effector memory T cells, enhancing the tumour immune response and slowing tumour progression." (PMID 39778006, 2025). "For example, studies in breast cancer have shown that increased flux through the HBP, along with higher levels of GFAT and HAS2, enhances Akt/GSK3β/β-catenin signaling and increases O-GlcNAcylation, promoting cancer stem–like properties." (PMID 41461315, 2025). "In this study, 12 different indole‐substituted maleimide derivatives were designed, synthesized, and MTT tests were performed in two different breast cancer cell lines (MCF‐7 and MDA‐MB‐231) to determine their GSK‐3β inhibitor activities." (PMID 39313991, 2024). "In a study of breast cancer, PD-L1 inhibited GSK3β function by binding and inhibiting the tyrosine phosphatase PTP1B, thus preventing the GSK3β-mediated degradation of Snail." (PMID 38729997, 2024). "bacciferum suppressed the GSK3β and Wnt2 signaling pathways in MCF-7 breast cancer cell lines, acting as an anti-metastatic and anticancer agent." (PMID 38800305, 2024). "For example, in breast cancer, EGF-induced inactivation of GSK3β induces an increase in PD-L1 glycosylation, maintaining stable PD-L1 expression." (PMID 38762484, 2024). "The effects of combining two GSK3β inhibitors, namely 9-ING-41 and 9-ING-87, with chemotherapy were examined on breast cancer cells." (PMID 37205308, 2023). "EGFR-activated AKT inhibits GSK3β activity via Ser9 phosphorylation, suppresses EGF signaling in basal-like breast cancer (BLBC) cells, reduces PD-L1 stability, and decreases cancer cell immune escape, thereby demonstrating a therapeutic benefit." (PMID 37554324, 2023). "In PIK3CA-mutant ER+ breast cancer, PI3Kα signaling promotes INPP4B-dependent lysosomal degradation of GSK3β, which enhances Wnt/β-catenin activation." (PMID 37471270, 2023). "The Western blot analysis was used to evaluate the expression levels of PI3K, AKT, GSK3β, PTEN, and the phosphorylation levels of AKT at Ser473 and GSK3β at Ser9 in breast cancer cells." (PMID 37483742, 2023). "In breast cancer, MCF-7 and MDA-MB-231 cell lines, the silencing of Notch3 reduced GSK3β expression, which is sufficient to induce EMT." (PMID 36139447, 2022). "PTPN6 dampens the oncogenic characteristics of breast cancer by dephosphorylating STAT3 and inactivating the Ras/extracellular signal-regulated kinase (Erk)/glycogen synthase kinase-3beta (GSK-3β) signaling pathway." (PMID 35957898, 2022). "In addition, EGF could stabilize PD-L1 via GSK3β inactivation in basal-like breast cancer." (PMID 35280982, 2022). "Pertinent to our study, Notch3 was found to transactivate GSK3β and to inhibit EMT in a breast cancer cell model." (PMID 36497426, 2022). "Insulin signaling in various cell models (colorectal, liver, and breast cancer cells) was reported to be a potent transcriptional inducer that regulates SREBP-1 through Akt, mTORC1, and Gsk3β." (PMID 35631531, 2022). "Suppressed VCAN expression blocks breast cancer cell self-renewal, while overexpression of the G3-domain of VCAN promotes cancer cell self-renewal via the EGFR/AKT/GSK3β pathway." (PMID 36358747, 2022). "In an ER+ MCF-7 breast cancer model, the stable knockdown of PAD4 led to a decreased nuclear GSK3β level, activation of TGF-β signaling and the EMT, thereby enhancing the invasive potential of breast cancer cells." (PMID 36365233, 2022). "In our study, FGFR4 phosphorylated GSK-3β to activate β-catenin/TCF-4 signaling and drive anti-HER2 resistance in breast cancer." (PMID 35562334, 2022). "We found that phosphorylated GSK-3β was increased and WNT/β-catenin signaling was activated in trastuzumab-resistant breast cancer cell lines." (PMID 35562334, 2022).
breast cancer (continued). "Moreover, the data from breast cancer research indicated that expression of p-AKT and p-GSK-3β dramatically decreased in breast cancer cells upon DACT2 re-expression, which indicated DACT2 might regulate Akt/GSK-3 signaling pathway to involve in migration and invasion." (PMID 35864965, 2022). "For instance, in breast cancer cells, VCAN V2 expression suppressed Snail and induced E-cadherin protein levels through inhibition of the EGFR/ERK/GSK3β axis." (PMID 36358747, 2022). "Inhibition of the GSK3β activity suppresses the ligand-activated transcription of an AHR target gene in HeLa, human liver cancer (Hep3B), and human breast cancer (MCF-7) cells." (PMID 34198826, 2021). "In our study, we identified that PPA1 promoted breast cancer metastasis via Slug-mediated EMT, proceeding through the PI3K/AKT/GSK3β signaling pathway." (PMID 34595179, 2021). "For example, in hepatocarcinoma and breast cancer cells, the JNK pathway upregulates the lysil oxidase-2 (LOXL-2), which oxidizes Snail, preventing its phosphorylation by GSK-3β." (PMID 33800291, 2021). "In the following studies, we investigated the effects of GSK-3β expression on the sensitivity of the MIA-PaCa-2 pancreatic cancer and the MCF-7 breast cancer cell lines to various chemotherapeutic drugs, signal transduction inhibitors, and nutraceuticals." (PMID 33917370, 2021). "The p-AKT/GSK3β signaling pathway facilitates β-catenin nuclear translocation, OCT4 promoter binding, and OCT4 expression, which leads to enhanced breast cancer cell stemness." (PMID 33500726, 2021). "Collectively, these findings indicated that PPA1 facilitated breast cancer progression and EMT via activating PI3K/AKT/GSK3β signaling pathway." (PMID 34595179, 2021). "Taken together, we confirmed that PPA1 promoted breast cancer proliferation, migration, and invasion through PI3K/AKT/GSK3β signaling." (PMID 34595179, 2021). "Data from our work describe a novel regulator of breast DDCCs survival, EphB6, that modulates adaptation to lung microenvironment through the GSK3β-TFEB-lysosomal axis, providing potential novel liabilities of disseminated dormant breast cancer cells." (PMID 33802447, 2021). "In our previous studies with MCF-7 breast cancer cells, we compared the levels of GSK-3β protein and the extent of S9-phosphorylated GSK-3β protein, which is an indicator of its activity, by western blot analysis." (PMID 33917370, 2021). "As expected, we found that GSK3β or PGK1 depletion using their siRNAs significantly induced ALDH1A1 expression, suggesting that both GSK3β and PGK1 negatively modulated the stemness of breast cancer cells." (PMID 34403222, 2021). "Based on the report of RPN2 physical interaction and subsequent functional suppression in breast cancer, we explored role of RPN2 in the GSK-3β/wnt/β-catenin pathway." (PMID 33087705, 2020). "shACTN4 suppresses the Akt/GSK-3β/β-catenin signaling, and ACTN4 interacts with β-catenin in breast cancer stem cells." (PMID 33363146, 2020). "Studies had shown that degrading PTEN through lysosome-mediated activation of PI3K/AKT/GSK3β/SNAI1 signaling pathway could promote the metastasis and progression of EMT and breast cancer tumors, which showed that the loss of PTEN contributed to the development of breast cancer." (PMID 30713576, 2019). "In this study, we found that knocking down lncRNA‐ZEB2‐AS1 results in the down‐regulation of ZEB2 expression through the PI3K/Akt/GSK3β/Zeb2 signaling pathway, inactivation of AKT and GSK3β phosphorylation, inhibition of EMT in breast cancer." (PMID 30825262, 2019). "GSK3β knockdown by shRNA interference hinders generation of malignancy and enhances autophagy though the AMPK pathway in breast cancer." (PMID 31683987, 2019). "In breast cancer, Ecto-5′-nucleotidase overexpression enhanced AKT/GSK-3β/β-catenin/cyclinD1 signaling pathway." (PMID 30992388, 2019).